MMP9 (matrix metallopeptidase 9)
Diseases named in the same sentence as MMP9 in open-access papers (continued):
Sharing a sentence is not in itself a finding about the gene and the disease.
osteosarcoma (continued). "This study found MMP9 was the most related hub gene in the progression of osteosarcoma." (PMID 34261456, 2021). "The ANGPTLs were reported to regulate the expression of MMP9 in osteosarcoma and HCC." (PMID 33413536, 2021). "Meanwhile, this study filled the gap in research of MMP9 in osteosarcoma." (PMID 34261456, 2021). "Our results provide prognostic value of MCP-1 in osteosarcoma by promoting MMP-9 expression." (PMID 33228783, 2020). "Furthermore, TSP‐2 appeared to promote MMP‐9 expression by which promotes cell migratory potential in osteosarcoma cells." (PMID 33021341, 2020). "Additionally, circulating MMP-2 seems to alter sensitiveness of osteosarcoma cells in chemotherapeutic drugs as a shift from MMP-9 to MMP-2 secretion is correlated with poor response to them." (PMID 32377334, 2020). "Our findings indicate that MCP-1 induces MMP-9 expression in osteosarcoma cells." (PMID 33228783, 2020). "The expression levels of MMP-9 among migration-prone subclone, osteosarcoma cell lines and normal osteoblasts were also evaluated, and our results indicated that MCP-1 expression was positively associated with MMP-9 expression." (PMID 33228783, 2020). "We also found positive correlation between TSP‐2 and MMP‐9 in osteosarcoma cells." (PMID 33021341, 2020). "However, up until now, it has been unclear as to what role of MMP‐9 plays in osteosarcoma progression." (PMID 33021341, 2020). "Therefore, AP-1 was an essential mediator in MCP-1-promoted MMP-9 upregulation and osteosarcoma migration." (PMID 33228783, 2020). "Furthermore, we found that TSP‐2 increased the levels of matrix metallopeptidase 9 (MMP‐9) expression and thereby increased the migratory potential of human osteosarcoma cells." (PMID 33021341, 2020). "Our findings implied that MMP-9 attenuation might be a new therapeutic target for osteosarcoma metastasis." (PMID 33228783, 2020). "Additionally, MMP-9 has been found to be involved in osteosarcoma cell invasion, with a highly predictive role in the development of lung metastases, especially when co-expressed with chemokine CXCR4." (PMID 32377334, 2020). "In addition, MMP2 and MMP9 were subsequently upregulated through the c-jun pathway, and this finally promoted the migration and invasion ability of osteosarcoma cells." (PMID 31930127, 2019). "Tumor progression-associated proteins (VEGF, MMP-9, Cyclin-D1, C-FLIP, MCL-1, and XIAP) may serve as therapeutic targets for inhibition of osteosarcoma progression." (PMID 31238539, 2019). "Our current results also presented that both PD98059 (MEK/ERK pathway inhibitor) and miltefosine (AKT inhibitor) both inhibit the expression of tumor progression-associated proteins (VEGF, MMP-9, Cyclin-D1, C-FLIP, MCL-1, and XIAP) in osteosarcoma U-2 OS cells in vitro." (PMID 31238539, 2019). "Notably, both RhoA and MMP-9, which are positively regulated by Skp2 and play a role in osteosarcoma invasion, were suppressed following Skp2 knockdown." (PMID 30250282, 2018). "In osteosarcoma cells, SIRT6-mediated invasiveness was associated with MMP9 signaling." (PMID 30524965, 2018). "Therefore, in attempt to inhibit the invasion, angiogenesis, metastasis of osteosarcoma, Wogonin has met to anti-cancer expansion via down-regulation of MMP-9." (PMID 28606135, 2017). "Interestingly, tectorigenin has been shown to inhibit cell migration through downregulation of MMPs, including MMP-2 and MMP-9, in osteosarcoma cells." (PMID 28264481, 2017). "In this work, we showed that baicalein could not only reduce the protein expression but also decrease the enzymatic activity of MMP-2 and MMP-9, this results could partially explain the decline in osteosarcoma motility after treatment with baicalein." (PMID 29156780, 2017). "Therefore, the down-regulation of MMP-2 and MMP-9 is related to the inhibition of osteosarcoma cell metastasis and is partly attributed to EMT reversal." (PMID 27144433, 2016).
osteosarcoma (continued). "To explore whether TSG101 depletion has the same effects in other cell lines as in HT1080 cells, we examined the effect of TSG101 depletion on MMP-9 mRNA expression in U2OS osteosarcoma and HeLaS3 cervical carcinoma cells." (PMID 26608825, 2015). "MMP-2 and MMP-9 have been studied often in the context of osteosarcoma and pulmonary metastasis." (PMID 26202311, 2015). "High MMP-9 expression was observed in pretreatment osteosarcoma tumor samples and in most metastatic lesions, leading to the speculation that MMP-9 is associated with the micrometastatic behavior of osteosarcoma." (PMID 23764122, 2013). "The possible correlation between pre-ALP levels and osteosarcoma MMP-9 expression was examined." (PMID 22333159, 2012). "Given that MMP-2 and MMP-9 are instrumental in tumor cell invasion, our results suggest the risedronate could reduce osteosarcoma cell invasion." (PMID 19624845, 2009). "Moreover, wogonin was able to affect the expression of matrix metalloproteinase 9 (MMP–9) in osteosarcoma stem cells, a protein involved in the degradation of the extracellular matrix (ECM) and promoter of the angiogenesis necessary for malignant cells invasion." (PMID 35956961, 2022). "In summary, our study revealed that inhibition of GSK-3β might suppress the osteosarcoma invasion and migration via the pathways associated with PTEN and phosphorylation of focal adhesion kinase, followed by reduced expression of MMP-2 or MMP-9." (PMID 33969873, 2021). "It is noteworthy that not only MMP9 could be served as therapeutic target, but other related hub genes identified in this study have these potentials for inhibitors design to prevent the development of Osteosarcoma." (PMID 34261456, 2021). "Moreover, with MMP-9 inhibitor (SB-3CT), less osteosarcoma cell migration was demonstrated." (PMID 33228783, 2020). "Therefore, MCP-1 triggered osteosarcoma metastasis through the regulation of MMP-9 expression." (PMID 33228783, 2020). "Consequently, MMP-9 is yet another protease that could be involved in the osteosarcoma-induced processes." (PMID 33154487, 2020). "It indicated that MMP-9 could be a potential biomarker for osteosarcoma." (PMID 30262739, 2018). "In order to delineate the mechanisms underlying downregulation of MMP9 and MMP2 after PC4 knockdown, and to confirm that these results were not restricted to the 143B tumor cell line, we measured fibronectin mRNA levels in seven osteosarcoma cell lines after PC4 knockdown." (PMID 28881805, 2017). "A shift from MMP9 to predominant MMP2 activity is associated with poor response to chemotherapy suggesting that the ratio of MMP2/MMP9 activity might be a valuable and easily accessible marker to predict the response to chemotherapy in osteosarcoma." (PMID 26979530, 2016). "Among the more than 20 known members of the MMP family, especially MMP2 and MMP9 have been extensively studied in human cancers and have been shown to be closely related to the invasive potential and metastasis of different types of tumor cells including osteosarcoma." (PMID 26979530, 2016). "In osteosarcoma, upregulation of MMP-2, MMP-9, and MMP-13 has been observed in the presence of RUNX2, which promotes metastasis and invasion." (PMID 40806771, 2025). "The observed reduction in osteosarcoma cell migration was corroborated by the molecular analysis of ECM-degrading enzymes, particularly MMP9 and MMP13." (PMID 40332124, 2025). "In our study, Tas and PCI significantly suppressed MMP9 and MMP13 expression, leading to reduced osteosarcoma cell migration and invasion, as evidenced by the wound healing assays." (PMID 40332124, 2025). "For example, in an osteosarcoma cell line study, RUNX2 silencing inhibited invasion capacity by suppressing VEGF, MMP-2, and MMP-9 expression." (PMID 40806771, 2025).
osteosarcoma (continued). "At the same time, the activation of NF-κB can further up-regulate the expression of some genes related to tumor cell proliferation and metastasis, such as MMP-9 and VEGF, and enhance the malignancy of osteosarcoma." (PMID 40786506, 2025). "The released p50/p65 complex up-regulates the expression of metastasis-related genes such as MMP-9 and CXCR4 after entering the nucleus, ultimately promoting the migration ability of osteosarcoma cells." (PMID 40786506, 2025). "For instance, Circ_001621 attenuated the restraint of matrix metallopeptidase 9 (MMP9) and cycling-dependent kinase 4 (CDK4) by miR-578, thereby increasing osteosarcoma proliferation and migration, respectively." (PMID 39944836, 2025). "Similar results were also obtained in osteosarcoma MG-63 cells, where results pointed toward a role of melatonin in suppressing the EMT via HIF-1α/Snail/MMP-9 signaling." (PMID 38473317, 2024). "MMP overexpression (specifically MMP-2, MMP-9, or MMP-13) is a promising indicator for prognosis and pulmonary metastasis in osteosarcoma." (PMID 38816365, 2024). "Aripiprazole has been shown to inhibit metastatic behavior in human osteosarcoma cells by reducing MMP-2 and MMP-9 expression levels and activity." (PMID 38816365, 2024). "The in vivo and in vitro lentivirus-mediated siRNA reduction of MALAT1 expression decreases in PCNA, MMP-9, p-PI3K, and RhoA/ROCKs expression, which then attenuates the growth, invasion, and dissemination of osteosarcoma cells." (PMID 39015175, 2024). "Glabridin inhibits osteosarcoma cell migration and invasion by suppressing p38 and JNK pathway activation, preventing CREB-AP1 complex formation, and reducing MMP-2 and MMP-9 expression." (PMID 39723390, 2024). "Studies have shown that MMP-9 can facilitate ECM degradation, allowing osteosarcoma cells to penetrate the ECM and metastasize to other tissues and organs." (PMID 37893141, 2023). "For example, MMP-9 facilitates ECM degradation, enabling osteosarcoma cells to penetrate the ECM and metastasize to other tissues and organs." (PMID 37893141, 2023). "In osteosarcoma, COX-2 affects the expression levels of vimentin, E-cadherin, MMP-9 and MMP-2 by activating the PI3K/AKT/NF-κ b signaling pathway, leading to a significant increase in the migratory ability of osteosarcoma cells." (PMID 37404761, 2023). "Studies have determined that aprepitant has the ability to inhibit the migrative ability of osteosarcoma tumor cells and reduce the levels of matrix metalloproteinases (MMP-2 and MMP-9), as well as NF-κB, a known stimulator of metastasis-related genes." (PMID 36983138, 2023). "High levels of zymogen precursors of MMP-2 and MMP-9 as well as active MMP-2 were found in most canine tumors, including osteosarcoma." (PMID 37048099, 2023). "MMP9 and Bcl-2 can be regulated by c-Jun and participate in CREB3-c-Jun modulated osteosarcoma progression." (PMID 37197432, 2023). "In osteosarcoma, piperine inhibited cell migration by reducing the expression of MMP2 and MMP9 and increasing the expression of TIMP1 and TIMP2." (PMID 36678600, 2023). "We observed that aprepitant inhibited the migrative phenotype of osteosarcoma cells and reduced the expression levels and activities of matrix metalloproteinases (MMP-2 and MMP-9)." (PMID 36177059, 2022). "Competitive binding of lnc-SELPLG-2:1 to hsa-hsa-miR-10a-5p prevented BTRC from miRNA-mediated degradation, thereby activating the expression of VIM, MMP9, and MMP2, promoting osteosarcoma cell proliferation, migration, and invasion, and inhibiting apoptosis." (PMID 36199080, 2022). "It was consistent with publications that apatinib inhibited cell migration and invasion by blocking the expression of Slug, snail and MMP9 in the cholangiocarcinoma (CCA) cell lines, and suppressed EMT in osteosarcoma." (PMID 35315581, 2022). "For example, in osteosarcoma cells, RAP2 enhances cell migration and invasion via increasing MMP2 and MMP9 expression." (PMID 35538031, 2022).
osteosarcoma (continued). "We also observed that aprepitant inhibited the migrative phenotype of osteosarcoma cells and reduced the expression levels and activities of matrix metalloproteinases (MMP-2 and MMP-9)." (PMID 36177059, 2022). "We suggested that the antimetastatic effect of aprepitant in osteosarcoma is probably attributed to its ability to modulate the transcriptional regulator, NF-κB, and subsequently, its target genes, including MMP-2, MMP-9, and VEGF-A." (PMID 36177059, 2022). "CCN4 also promotes migration, invasiveness and metastasis of osteosarcoma cells upregulating MMP-2 and MMP-9 expression." (PMID 34228239, 2021). "In a past study of metastatic human osteosarcoma cells, quercetin clearly diminished expression of PTHR1 mRNA, thus attenuating expression levels of MMP‐2 and MMP‐9 mRNA and ultimately reducing cellular invasion, adhesion, proliferation and migration." (PMID 33675132, 2021). "Our study revealed that cordycepin and cisplatin synergistically inhibited osteosarcoma cell invasion and invasion by downregulating MMP-2 and MMP-9 expression." (PMID 34953496, 2021). "Functional experiments and mechanistic studies revealed that circ_001621 promoted the proliferation and migration of osteosarcoma cells in vitro via attenuating miR‐558‐mediated repressing of VEGF and the downstream expression of CDK4 and MMP9." (PMID 33103338, 2021). "Studies have shown that MMP-2 and MMP-9 are involved in AKT/mTOR-mediated invasion and metastasis of osteosarcoma cells." (PMID 34953496, 2021). "In conclusion, their results demonstrated that curcumin exerts an inhibitory effect on osteosarcoma cell proliferation and invasion by inhibition of Notch-1 signaling, following the suppression of Hes-1, cyclin D1, MMP-2, and MMP-9 expression." (PMID 34671398, 2021). "We found that cordycepin significantly reduced the protein expression levels of Bcl-2, MMP-2, and MMP-9 and induce increased the expression levels of Bax, and Cleaved PARP in osteosarcoma cells." (PMID 34953496, 2021). "Over-expression of miR-181a leads to increased viability of osteosarcoma cells and induced cell proliferation by augmenting BCL2, MMP9; and apoptosis was inhibited by down-regulation of p21 and TIMP3 expression." (PMID 32932883, 2020). "Therefore, we hypothesized that MMP-9 are key mediators in MCP-1-induced osteosarcoma migration." (PMID 33228783, 2020). "Our data demonstrate higher TSP‐2 expression in osteosarcoma tissue than in normal bone tissue, and also confirm TSP‐2 has capacity to increase MMP‐9 expression, by which to enhance cell migratory potential in osteosarcoma disease." (PMID 33021341, 2020). "This study suggested that MCP-1 promoted osteosarcoma migration through the CCR2 receptor and the upregulation of MMP-9 expression through c-Raf, MAPK, c-Jun, and AP-1 activation." (PMID 33228783, 2020). "Osteosarcoma cells pre‐treated with an MMP‐9 monoclonal antibody (mAb), an MMP‐9 inhibitor, or transfected with MMP‐9 small interfering RNA (siRNA) reduced the capacity of TSP‐2 to potentiate cell migration." (PMID 33021341, 2020). "A previous study reported that TA3 attenuates the migration of MG63 osteosarcoma cells via the inhibitions of gelatinases (MMP-2 and MMP-9) via transcriptional suppression." (PMID 32774433, 2020). "Osteosarcoma cells proved to be sensitive to doxycycline exposure, as MMP-2 and MMP-9 secretion were suppressed in a dose-dependent manner." (PMID 32377334, 2020). "The MMP-9 expression in stage II and stage III osteosarcoma cells was 2–3 and 3–4 times, respectively, higher than that in normal tissue." (PMID 33228783, 2020). "To identify the mediator of MCP-1-promoted osteosarcoma migration, we further examined the expression of MMP-1, MMP-2, MMP-3, MMP-7, MMP-9, MMP-12, and MMP-13 mRNA under MCP-1 stimulation." (PMID 33228783, 2020).
osteosarcoma (continued). "To identify the mediator of TSP‐2‐promoted osteosarcoma migration, we examined levels of MMP‐1, MMP‐2, MMP‐3, MMP‐7, MMP‐9, MMP‐12 and MMP‐13 mRNA expression following TSP‐2 stimulation." (PMID 33021341, 2020). "Studies have revealed that MMPs including MMP-1, MMP-2, MMP-3, MMP-7, MMP-9, MMP-12, and MMP-13 are significantly related to osteosarcoma metastasis and poor prognosis." (PMID 33228783, 2020). "To investigate the effects of BD on osteosarcoma invasive ability in vivo, we evaluated lung metastasis and detected the expression of MMP‐2 and MMP‐9 in different groups." (PMID 31631559, 2019). "The ability of the osteosarcoma cell line Saos-2 to induce new blood vessel formation by upregulation of angiogenic growth factors like VEGF165, FGF2, MMP2 and MMP9 has already been shown." (PMID 30986223, 2019). "We also previously demonstrated that, by controlling MMP2/MMP9 expression and activity, the JNK/c-Jun signaling pathway plays a key role in osteosarcoma potential for metastasis." (PMID 30642298, 2019). "Several studies have highlighted that the invasive capacities of osteosarcoma cells are correlated with MMPs expression, particularly MMP-2 and MMP-9." (PMID 31370265, 2019). "Specifically, we demonstrate here that WIN markedly reduced the migratory ability of osteosarcoma MG63 cells, and this effect was accompanied by a dramatic reduction in the extracellular activity and intracellular levels of MMP2 and MMP9 metalloproteases." (PMID 31652569, 2019). "In vitro assays showed that IRX2 upregulated MMP-9 and VEGF in a PI3K/AKT-dependent manner, and that knockdown of IRX2 in osteosarcoma cell lines inhibited cell proliferation and invasion." (PMID 30760827, 2019). "Nobiletin inhibits human osteosarcoma U2OS and HOS cells’ motility, migration and invasion by down-regulating MMP-2 and MMP-9 expressions via ERK pathways." (PMID 30960968, 2018). "Suppression of miR-506-3p in osteosarcoma led to increased expression of RAB3D, which in turn led to increased CDK4 (cyclin-dependent kinase 4) and MMP9 (matrix metalloprotein 9) activities." (PMID 29905536, 2018). "Wogonin induces apoptosis of human osteosarcoma CSC, inhibits its mobility in vitro via downregulation of MMP-9 expression, and represses its renewal ability." (PMID 28606135, 2017). "To further confirm the role of FAK signaling in TSP1-induced osteosarcoma cell migration and invasion, we detected the MMP2, MMP9 and FN1 expression in Well5 and U2OS cells after FAK were silenced by siRNAs." (PMID 29100277, 2017). "In various osteosarcoma cells, PC4 knockdown reduced MMP9 and MMP2 mRNA levels, compared to each parental cell respectively (Figure 5A1-5A4)." (PMID 28881805, 2017). "Relaxin-2 (RLN2) increases osteosarcoma cell migration, invasiveness, proliferation, and participates in the activation of the S100A4/MMP-9 signaling." (PMID 29069865, 2017). "Nobiletin inhibits human osteosarcoma cells motility, migration and invasion by down-regulating MMP-2 and MMP-9 expressions via ERK and JNK pathways." (PMID 28938584, 2017). "Analysis of MMP expression and activity in osteosarcoma cell lines, biopsies and xenografts revealed a strong expression of MMP2 in culture supernatants from cell lines and in tumor xenografts while MMP9 expression was below the detection limit." (PMID 26979530, 2016). "The present study sought to determine the anti-metastatic effect of nobiletin on the human osteosarcoma cells in vitro by monitoring the regulation of MMP-2 and MMP-9 expressions and the possible signaling pathways." (PMID 27144433, 2016). "However, a recent meta-analysis including 18 studies covering 892 osteosarcoma patients demonstrated that although MMP9 might be a potential biomarker for osteosarcoma, a substantial heterogeneity exists among the different studies that could be attributed mainly to methodical issues." (PMID 26979530, 2016).